ESR1 (estrogen receptor 1)
Diseases named in the same sentence as ESR1 in open-access papers (continued):
Sharing a sentence is not in itself a finding about the gene and the disease.
breast cancer (continued). "We found that the T genotype of PvuII (rs2234693) in ESR1 was associated with a better OS and a trend for better DFS than the C genotype in postmenopausal, hormone receptor positive early breast cancer patients treated with adjuvant exemestane alone in the TEAM study." (PMID 33547330, 2021). "Based on these findings, we suggest that the elevated NUPR1 protein level may provide a novel biomarker for Tam resistance in ESR1-positive breast cancer cells." (PMID 33542201, 2021). "Analysis of correlations between variants in the ESR1 region show SNPs associated with age at first birth, age at menarche or breast cancer are not likely to result from the same causal variants as the SNPs associated with endometriosis risk." (PMID 33806348, 2021). "In another study, the CellSearch® and DEPArrayTM systems were combined in order to isolate single CTCs from ER-positive metastatic breast cancer patients; using MALBAC and Sanger Sequencing, 14 ESR1 hotspot mutations were detected, and their presence was correlated with endocrine resistance." (PMID 33535614, 2021). "In a phase II clinical trial (PALOMA-1), the addition of palbociclib to letrozole significantly increased the median progression-free survival (PFS) from 10.2 months to 20.2 months vs. letrozole alone for post-menopausal women with previously untreated ESR1+/HER2− advanced breast cancer." (PMID 34445095, 2021). "Furthermore, we screened three mRNAs (ESR1, ADRA2A, and DTL) associated with breast cancer drug resistance from key genes." (PMID 34490040, 2021). "Specific examples of ESR1 fusion–induced genes in the MOTERA signature that are related to metastasis include SGK1, which encodes serum- and glucocorticoid-inducible kinase 1 and promotes breast cancer bone metastasis." (PMID 34711608, 2021). "Variation in the ESR1 gene may therefore be a prognostic marker of early breast cancer survival, and warrants further research." (PMID 33547330, 2021). "Taken together, this study defines acquired genomic changes in long-term, estrogen-deprived disease; highlights the importance of longitudinal RNA profiling; and identifies a common ESR1-depleted endocrine-resistant breast cancer subtype with basal-like transcriptional reprogramming." (PMID 33407744, 2021). "This negative regulation of ESR1 gene expression reinforces the hypothesis that ESR1 heterogeneity between different breast cancer types is due to the establishment of distinct epigenetic marks." (PMID 34831189, 2021). "Clinically, ESR1 is used to define the ER status of breast cancer." (PMID 35252218, 2021). "In addition, Gene Set Enrichment Analysis (GSEA) also revealed that breast cancer with USP35-high expression was enriched in ESR1 up and luminal B up breast cancer." (PMID 34131114, 2021). "Additionally, others demonstrate in human breast cancer cells that ERß inhibits ESR1 expression through binding to the Sp-1 transcription factor and recruiting a co-repressor to the ERα gene promoter, effectively halting transcription." (PMID 34769153, 2021). "The most recent breast cancer GWAS identified a 2–5 fold increased enrichment of risk SNVs in REs, mostly mapping to the binding sites for breast cancer–associated transcription factors including FOXA1, ESR1, GATA3, E2F1, and TCF7L2." (PMID 34439109, 2021). "However, much remains to be uncovered to better understand how ESR1 expression is regulated in breast cancer." (PMID 34831189, 2021). "Importantly, our observed correlation between ERBB2 and ESR1 expression patterns and pCR resembles that shown for breast cancer tissues from patients receiving NAC with very similar cut-offs." (PMID 34073233, 2021).
breast cancer (continued). "The ESR1 PvuII TC + CC genotypes confer poor prognosis in advanced breast cancer, but these genotypes could be regarded as a good predictor of the therapeutic effect of hormonal treatment." (PMID 34930150, 2021). "Indeed, when estrogen receptor alpha gene (ESR1) fusion proteins is expressed in breast cancer cell lines it promotes an estrogen-independent activation of EMT by Snail upregulation and E-cadherin downregulation." (PMID 34003341, 2021). "Taken in context, this suggests that a genistein-supplemented regimen for treating breast cancer can be beneficial; however, it might be contraindicated for women whose tumors present with a high ESR1/ESR2 ratio." (PMID 34578926, 2021). "In addition to breast cancer, ESR1, ESR2, and PGR also mediate the progression of prostate cancer, colon cancer, ovarian cancer, and lung cancer." (PMID 34322374, 2021). "We have shown previously that mutations in PIK3CA and ESR1 in advanced ER+ breast cancer previously treated with endocrine therapy do not predict response to palbociclib." (PMID 32940689, 2021). "(A) Correlation of HSF1 and ESR1 transcript level in all TCGA breast cancers." (PMID 34783649, 2021). "Our data indicate that NUPR1 depletion in ESR1-positive breast cancer cells overcomes Tam resistance; however, we do not know the exact functional associations of this protein except for those with ESR1." (PMID 33542201, 2021). "ESR1 hypermethylation is also correlated with poor prognosis and drug response in breast cancer." (PMID 34778269, 2021). "Identifying novel therapeutic targets based on cancer vulnerabilities remains a promising strategy to effectively delay disease progression and improve outcome of ERα-positive breast cancer patients regardless of the presence of ESR1 mutations." (PMID 34944934, 2021). "Interestingly, a recent publication, revealing the role of menin in regulating the enhancer of the ESR1 gene coding for ERα, suggests distinct functions for menin in primary normal mammary cells and in breast cancers." (PMID 34561764, 2021). "In breast cancer patients treated with aromatase inhibitors, the screening of CYP19A1, CYP17A1, CYP27B1, TCLA1, RANK/RANKL/OPG, and ESR1/ESR2 variants may be of some utility to optimize positive effects and reduce ADRs." (PMID 34948113, 2021). "Candidate pathways were constructed starting from the estrogen receptor ESR1 gene and targeting breast cancer-associated transcription factors, such as JUN, FOS, STAT1, STAT3, STAT5A, ELK1, and ETS1 (Target transcription factors were pre-identified by GibbsOS19)." (PMID 33432018, 2021). "Preliminary, variations of ESR1 gene have been described in low aggressive mammary tumors." (PMID 33652604, 2021). "Breast cancer groups bearing germline and somatic BRCA2 mutations as well as non-mutated patients were characterized by the upregulation of luminal subtype signatures such as ESR1, TFF1, TFF2." (PMID 33525353, 2021). "This suggests that genistein may have the potential to elicit counterproductive effects in women already being treated for a high ESR1/ESR2 ratio breast cancer using these common over-the-counter therapeutics." (PMID 34578926, 2021). "At the individual gene level and compared to controls, ATF3-induced mammary tumors exhibited reduced expression of Rb1, Esr1, and Pgr, and increased expression of Erbb2, Egfr, and the genes encoding keratins 5, 6, and 17, which is similar to basal-like human breast cancer tumors." (PMID 33652981, 2021). "Targeting the NUPR1-mediated autophagic regulation may render ESR1-positive breast cancer cells more sensitive to antiestrogen therapy." (PMID 33542201, 2021). "GATA3 and FOXA1 are marker genes that define an ESR1-positive breast cancer." (PMID 34395436, 2021). "A new problem was arisen whether there are genes in common that correlate with ESR1, DNAJC12, and ERBB4 expression in breast carcinoma, the cBioPortal tool was first used to output the lists containing genes related to ESR1, DNAJC12, or ERBB4." (PMID 33718139, 2021).
breast cancer (continued). "In fact, the transcriptional levels of ESR1 are clearly decreased in relapsed tumor lesions when compared to primary tumors in tamoxifen-treated ER+ breast cancers, which suggests a possible transcriptional inhibition of ESR1 during acquired resistance to tamoxifen." (PMID 32210163, 2020). "Estrogen signaling plays a key role in BC carcinogenesis and it is mediated by two receptors belonging to the nuclear receptor superfamily: ERα and ERβ, encoded by the ESR1 and ESR2 genes, respectively, that play opposite roles in hormone-responsive breast cancer progression." (PMID 32260128, 2020). "Targeting these regulatory molecules may shut down mutant ESR1 gene expression and inhibit the growth of endocrine-resistant breast cancer." (PMID 32265480, 2020). "However, the transcript level of ESR1 was much lower in 621–101 cells than that in breast cancer MCF-7 cells, similar to previous findings." (PMID 32078667, 2020). "The intersection identified a total of 2 differentially expressed genes, including FABP7 and ESR1, might be essential indicators of chemotherapeutic efficacy in breast cancer." (PMID 33292226, 2020). "Diverse ESR1 gene fusion transcripts have been identified in luminal breast cancer cases." (PMID 33233830, 2020). "We found weak evidence for the association of risk variants rs294174 (ESR1), rs16886165 (MAP3K1), rs2214681 (CNTNAP2), rs4237855 (VDR), rs9594579 (RANKL), rs8183919 (PTGIS), rs2981582 (FGFR2), and rs1799950 (BRCA1) with sporadic breast cancer." (PMID 33126731, 2020). "Moreover, the ESR1 promoter methylation in blood has proved useful in the diagnosis of lung and breast cancers." (PMID 32455834, 2020). "Less is known regarding ESR1 mutations status at the time of newly diagnosed HR+ breast cancer recurrence, specifically in non-metastatic loco-regional recurrence." (PMID 32014063, 2020). "Eleanors are produced in the LTED cells derived from breast cancer cell lines, and specifically accumulate around the ESR1 gene, where they may stimulate its transcription." (PMID 32047236, 2020). "We speculated that CCDC170 might have important functions and clinical significance in breast cancer, considering its relationship with ESR1." (PMID 33291081, 2020). "Our findings suggest that known candidate genes like FGFR2, ESR1, VDR, or BRCA2 could be associated with breast cancer in Uruguay and other admixed Latin American populations." (PMID 33126731, 2020). "While the function of ESR1 in breast cancer has been well studied, that of CCDC170 remains elusive." (PMID 33291081, 2020). "Existing breast cancer cell lines do not harbor ESR1 mutations naturally (cbioportal.org), even though some were derived from metastatic patients, prospectively because these patients were either untreated or treated prior to standard use of AIs in the 2000s." (PMID 32576280, 2020). "MSI2 promotes cell growth in breast cancer via increasing estrogen receptor 1 protein stability." (PMID 31952541, 2020). "ESR1 mutations were not identified in any of the 23 patients with early-stage ER+ breast cancer resistant to NET." (PMID 32309212, 2020). "Given that ESR1 and ESR2 encode for ER-α and ER-β, we investigated the correlation of the estrogen response early score with the expression of ER-α (ESR1) and ER-β (ESR2) genes in large breast cancer cohorts." (PMID 33260779, 2020).
breast cancer (continued). "In conclusion, the evidence from this study suggests that a potential miRNA-mRNA network may be involved in the effect of ESR1 on ERα positive breast cancer." (PMID 32500028, 2020). "Finally, 18 ERα positive breast cancer tissues were used to validate the relationship between ESR1-miRNA, miRNA-mRNA, and ESR1-mRNA pairs." (PMID 32500028, 2020). "In addition, miR-148a and miR-22 inhibit ESR1 expression to inhibit the viability and migration of breast cancer cells." (PMID 32759784, 2020). "To examine if the results seen above were produced due to suppression of ER alone, we accessed the microarray data from previously published experimental study [GSE37820] where estrogen receptor alpha (ESR1) was knocked down in MCF7 breast cancer cells using siRNA." (PMID 32543775, 2020). "First of all, we determined expression levels of ESR1 in these breast cancer samples." (PMID 32500028, 2020). "d Correlations of LMTK3 expression with ESR1 in TCGA breast cancer patients." (PMID 30944027, 2019). "In conclusion, these findings suggest that the combination treatment of Doxorubicin, E2 and TNFα may be involved in decreasing the expression and activity of ESR1, potentially enhancing the chemotherapy efficacy in ER positive breast cancers." (PMID 31645610, 2019). "Therefore, the objective of the present study was to investigate the association between certain ESR1, ESR2, HER2, UGT1A4, and UGT2B7 single nucleotide polymorphisms and breast cancer." (PMID 31888550, 2019). "Reported ESR1 amplification rates in breast cancer range from 0% to 75% of patients." (PMID 30995757, 2019). "Elevated SETER/PR was associated with prolonged sensitivity to endocrine therapy in patients with metastatic HR+/HER2− breast cancer, especially in the absence of mutated ESR1 transcript." (PMID 31231679, 2019). "AR-mediated DSBs in prostate cancer may provide clues to the recurrent ESR1 breakpoints for ESR1 fusions seen in breast cancer." (PMID 31106278, 2019). "A recent study on breast cancer cells suggested that low levels of ESR1 promoters methylation may favor ESR1 gene expression (mediated by binding of progesterone to the promoter region)." (PMID 31261650, 2019). "Our data suggest that the ESR1 genetic profile may help on the decision regarding the selection of individual tailored preventive measures against canine mammary tumors development, such as early neutering." (PMID 31506083, 2019). "Estrogen signaling through ESR1, also known as ERα, is well known in human breast cancers." (PMID 31202267, 2019). "ESR1 gene dosage was examined by qPCR in 402 samples of primary breast cancers." (PMID 30995757, 2019). "Two genes have some association to cancer but not to CRC: PPARGC1B is a co‐activator for ESR1 and variants in the gene have been associated with increased risk for estrogen‐positive breast cancer." (PMID 30809968, 2019). "ESR1 fusions that contain the first six exons of ESR1 fused in-frame to partner genes are almost exclusively observed in endocrine therapy resistant, metastatic ER+ breast cancer, with the exception of ESR1-e6>NOP2 likely suggesting a role in driving disease pathogenesis." (PMID 31106278, 2019). "The presence of ESR1 amplification in some breast cancers is undeniable." (PMID 31106278, 2019). "c Correlations of LMTK3 expression with ESR1 in 2509 METABRIC breast cancer patients." (PMID 30944027, 2019). "Developing less toxic agents that target TOP2B may represent a therapeutic strategy to prevent ESR1 translocation events and deserves further study in the context of ER+ breast cancer." (PMID 31106278, 2019).
breast cancer (continued). "This suggests that I2 supplementation favors the re-induction of ESR1 expression in breast cancer." (PMID 31319484, 2019). "Collectively, these studies deepen our understanding of how ESR1 alterations trigger breast cancer to become lethal metastatic disease and will guide development of therapeutic strategies to treat a subset of patients with tumors that contains these ESR1 alterations." (PMID 31106278, 2019). "In addition, we constructed an ingredients-targets-diseases network that show that RYNXC treated breast cancer by regulating the ESR1, PGR, and PTGS2." (PMID 30906412, 2019). "The gene FLJ43663 is functionally related to an important breast cancer associated gene, ESR1, but its methylation status has not been directly confirmed in breast cancer subtypes." (PMID 31480430, 2019). "Similar to MYB, both MYBL1 and MYBL2 are upregulated by ESR1 signaling in breast cancer cells." (PMID 30833639, 2019). "Finally, MYB, MYBL1 and MYBL2 were reported to be upregulated by ESR1 signaling in breast cancer cells." (PMID 30833639, 2019). "For example, ESR1-e6>DAB2 and ESR1-e6>GYG1 were both identified in metastatic ER+ breast cancer." (PMID 30089255, 2018). "Out of the eleven candidate target genes regulated by rs117245733, the FOXO1 gene is notable, as its expression in primary human endometrial stromal cells is regulated by ESR142 and it is a direct protein–protein interaction partner of ESR1 in breast cancer cells." (PMID 30194396, 2018). "Despite a moderate decrease of the PR levels in these cell lines, this slight decrease of PR was accompanied by a concomitant decrease of ESR1 expression compared to control cells, confirming the importance of PR levels in maintaining ESR1 expression in different breast cancer cell lines." (PMID 30301163, 2018). "RNA sequencing (RNA-seq) detects estrogen receptor alpha gene (ESR1) fusion transcripts in estrogen receptor-positive (ER+) breast cancer, but their role in disease pathogenesis remains unclear." (PMID 30089255, 2018). "Here, we explore whether bazedoxifene (BZA), a potent antiestrogen that retains some SERM properties, shows activity against breast cancer cells that express ESR1 somatic mutants." (PMID 30489256, 2018). "Furthermore, FOXA1, GATA3, ESR1 and SPDEF are reported as master regulators in FGFR2 signaling and breast cancer risk in ER+ cells." (PMID 29741575, 2018). "ESR1 chromosomal translocation events also occur in endocrine-resistant, metastatic breast cancer patients resulting in fusion proteins possessing the N terminus and DNA-binding domain (DBD) of ERα, but containing partners from various genes that replace the LBD." (PMID 29748621, 2018). "Of particular importance in ER+ breast cancer, miR-221/222 targets ESR1." (PMID 30214383, 2018). "YBX1 and CTPS1 as well as ESR1 and CTPS1 were found to be independently associated with the prognosis, supporting the idea that PRIN2 and PRIN5 play important roles in the prognosis of breast cancer patients." (PMID 30647855, 2018). "Finally, EGR1 and ESR1 mRNA abundance were strongly and negatively correlated in ER+ breast cancers analyzed using TCGA (Pearson’s R = -0.21; p = 2.7e-10)." (PMID 29614078, 2018). "Several types of gene fusions including ESR1 have been reported in ER+ breast cancers." (PMID 29464067, 2018). "Estrogen drives many ESR1+ breast cancers and is an enduringly useful therapeutic target." (PMID 30248920, 2018). "This suggests that PR through its binding to the ESR1 promoter and the enhancer-like intronic sequence could facilitate the interaction between these two genomic regions to enhance the ESR1 transcription in T47D breast cancer cells." (PMID 30301163, 2018).